NR1H3 (nuclear receptor subfamily 1 group H member 3)
Diseases named in the same sentence as NR1H3 in open-access papers (continued):
Sharing a sentence is not in itself a finding about the gene and the disease.
vitiligo (1 paper, 2023). Generalized well circumscribed patches of leukoderma that are generally distributed over symmetric body locations and is due to autoimmune destruction of melanocytes. "The aim of the current work was to evaluate the relationship between polymorphisms of the gene nuclear receptor subfamily 1 Group H member 3 (NR1H3) and the risk of vitiligo and phototherapy effects in the Chinese Han population." (PMID 36854764, 2023). "Do the polymorphisms in the NR1H3 gene contribute to the risk of vitiligo in Han Chinese individuals?" (PMID 36854764, 2023). "Is serum NR1H3 protein level associated with vitiligo severity and individualized treatment effects?" (PMID 36854764, 2023). "It has been reported that a polymorphism located at the 5′ untranslated region in NR1H3 is associated with susceptibility to vitiligo risk in the North Indian population." (PMID 36854764, 2023). "Considering the complexity of the pathogenesis of vitiligo and the insufficiency of functional research on LXR-α (the protein encoded by NR1H3 gene), follow-up research on the relationship between the NR1H3 gene and the pathogenesis of vitiligo is still needed." (PMID 36854764, 2023). "In addition, a couple of previous studies have revealed higher expression levels of NR1H3 in perilesional skin compared to the normal skin of vitiligo patients." (PMID 36854764, 2023). "Collectively, these studies show that NR1H3 might be a key gene in the pathogenesis of vitiligo." (PMID 36854764, 2023).
tumor (23 papers, 2016 to 2026). "NR1H2 and NR1H3 are hepatic nuclear receptors that have been associated with lipogenesis and tumor cell growth." (PMID 41557483, 2026). "By regulating lipid metabolism, NR1H3 controls macrophage polarization and the inflammatory response, thereby influencing the tumor microenvironment (TME)." (PMID 37780629, 2023). "After adjustments of age, stage, gender, race, and tumor purity, the level of macrophage infiltration (HR = 8.44, p = 0.002) and the expression of NR1H3 (HR = 0.73, p = 0.044) were independent prognostic factors in BRCA." (PMID 36699456, 2022). "We further analyzed the correlation of NR1H3 expression and monocyte/macrophage markers in tumor tissues using TIMER2." (PMID 36699456, 2022). "Then we analyzed the expression of NR1H3 in BRCA based on tumor subclasses using the UALCAN database." (PMID 36699456, 2022). "As an important member of NR1 subfamily, the role of NR1H3 in tumor microenvironment remains to be revealed." (PMID 36699456, 2022). "We used the GEPIA2 tool to combine all tumor expression data of TCGA and obtained the top 300 genes that correlated with NR1H3 expression." (PMID 36699456, 2022). "Among the ten tumor-related genes used in the risk model, TRIM15, NEK6, ISG15, RFC2, and NR1H3 were upregulated." (PMID 36189312, 2022). "Related studies have demonstrated that NR1H3 can impair the anti-tumor response by inhibiting the CCR7 expression on dendritic cells, suggesting a novel mechanism for immune escape." (PMID 34136377, 2021). "Next, more interestingly, NR1H3/LXRA was expressed at higher levels in ER-negative than in ER-positive tumours (two-tailed Mann–Whitney U test: p < 0.01)." (PMID 31683867, 2019). "We then set out to test if expression of a wider and unbiased set of LXR target genes correlated with NR1H3/LXRA or NR1H2/LXRB expression in ER-positive or ER-negative tumours." (PMID 31683867, 2019). "By contrast, NR1H3 is down-regulated in all PAM50 tumor groups relative to the normal mammary-gland." (PMID 26894976, 2016). "Intriguingly, in tumour tissue of WD-fed mice, while the expression of Nr1h3 was significantly induced, the mRNA levels of its target genes involved in cholesterol excretion Abcg5/8 and de novo lipogenesis (Srebp1c, Fasn, Scd1) were not changed between the two groups of mice." (PMID 38824560, 2024). "Tumor-associated myeloid cells exhibited higher transcriptional expression of molecules linked to the “find me” (G2A), “eat me” (CD93, TIM1, SCARF1, SLC2A1, GAS6, TREM2, AXL, C1QA), and downstream processing (NR1H3, ATG7, PPARG, ABCA1, PPARD, DOCK180) phases of efferocytosis." (PMID 36439171, 2022). "At the same time, NEK6 and NR1H3 might be downregulated in tumor tissues." (PMID 36189312, 2022). "Consistent with the bioinformatic prediction, GTF3C1, NR1H3, NTHL1, SNX, TMEM132A and WIZ expressions were markedly upregulated in the tumor group relative to the normal group." (PMID 41573564, 2025). "NR1H3 is also able to suppress the activity of the epidermal growth factor receptor (EGFR) promoter, reducing tumor cell growth and proliferation." (PMID 38023258, 2023). "The downregulated expression of IL-1, CTSW, NR1H3 and CCR8 (with HR < 1) indicated these molecules as tumor suppressors, whereas the upregulated expression levels of LY86, RABGEF1, CYFIP2 and SERINC3 (with HR > 1) indicated these molecules as oncogenes." (PMID 33816214, 2020). "No statistical difference was found in NR1H3 mRNA expression among different tumor stages (p > 0.05)." (PMID 36699456, 2022). "In addition, the NR1H3-mediated promotion of the epithelial-mesenchymal transition (EMT) and migration of tumor cells has been reported in several cancers." (PMID 34136377, 2021).
cancer (16 papers, 2010 to 2025). A tumor composed of atypical neoplastic, often pleomorphic cells that invade other tissues. "In line with our results, NR1H3 (LXRα) has also been classified as a cancer suppressor in numerous studies." (PMID 38062450, 2023). "Lastly, “Signal transduction” includes nuclear receptor signaling, including NR1H2 and NR1H3-mediated signaling, ErbB cancer signaling and p75 NTR death signaling; note that NOTCH signaling was reported previously." (PMID 36437990, 2022). "The TISIDB database was used to infer the correlations between expression of NR1H3 and immunomodulators/chemokines across human cancers." (PMID 36699456, 2022). "Our data are in line with experimental results previously published.NR1H3 was reported to be an onco-suppressor gene in various cancers." (PMID 36699456, 2022). "We found the association between NR1H3 expression and mutated FBXW7, which is one of the most frequently mutated genes in human cancers and its functional inactivation can lead to tumorigenesis." (PMID 36699456, 2022). "Here, we found the relations between abundance of 28 TIL types and expression of NR1H3 were strongly correlated across different human cancer types." (PMID 36699456, 2022). "Expression of NR1H3 was significantly lower in moderately differentiated cancers compared to postmenopausal controls (P < 0.01)." (PMID 29371332, 2018). "In addition, according to the clinical data of these cancer cases, we found that the lower expression of NR1H3, the more lymph node metastasis (p > 0.05)." (PMID 36699456, 2022). "Nuclear receptor LXR (lxralpha, NR1H3) is another transcriptional regulator of GLUT5 expression identified in mice and human that is thought to be a potential pharmaceutical target for selective modulation of GLUT5 expression in context to cancer and metabolic disease." (PMID 35387598, 2022). "With the exception of three clusters of NRs representing NR classes I (cluster I: RORC, VDR, PPARA, NR1D1, THRA, RORA, NR1H3; cluster II: RARB, PPARG, THRB) and III (cluster III: ESR1, PGR, AR, ESRRG), NR class was not a good determinate of NR expression patterns in the different cancer types." (PMID 32024906, 2020). "Indeed, expression of NR1H3 (LXR-α) showed a significant correlation with FDPS and EBP synthesis in lung cancer samples but not in normal lung samples (data not shown), suggesting a cancer-specific regulation of mevalonate pathway genes by LXR-α." (PMID 22211244, 2012).
infection (5 papers, 2017 to 2025). The state of being infected such as from the introduction of a foreign agent such as serum, vaccine, antigenic substance or organism. "Last, attending to the expression of regulators of cholesterol homeostasis (bottom), we observed a clear decrease in Nr1h3 and Srebf2 mRNA levels in response to infection, consistent with a scenario where cholesterol uptake and availability are high." (PMID 36453897, 2022). "The pro-inflammatory response activation is also supported by the downregulation of transcription factors such as Pparg, Nr1h3 (Lxr), and Rxra early after infection." (PMID 34281214, 2021). "Furthermore, in infection with type II parasites, up-regulation of Abcg4, a Chl export protein, and of liver X receptor alpha (Nr1h3), was revealed." (PMID 28459857, 2017). "Our results confirm the relevance of Rxra and its counterparts Nr1h3 (Lxra) and Pparg as early as one day post infection in livers of BALB/c mice, probably via the limitation of the pro-inflammatory response right after infection." (PMID 34281214, 2021). "The liver X receptor α (LXRα, also known as NR1H3) and the farnesoid X receptor (FXR, also known as NR1H4) interact with the retinoid X receptor (RXR) and play essential roles in fatty acid, cholesterol, sterol, bile acid and glucose metabolism, and both were observed downregulated upon infection." (PMID 33314005, 2021). "In a similar fashion, all of Spic−/− mice succumbed to intravenous infection with nonlethal dose of Spn6A (103 CFU) in 2 days, but there was no mortality in Nr1h3−/− mice." (PMID 40073120, 2025).
connective tissue disorder (2 papers, 2020 to 2024). A disease involving the connective tissue. "Intriguingly, two of the differentially methylated genes identified in case-control comparisons—NR1H3 (involved in lipid metabolism and inflammation) and TNXB (associated with connective-tissue disorders)—corresponded to those identified by our group." (PMID 32375223, 2020). "NR1H3 is involved in lipid metabolic processes, inflammation, and energy homeostasis, while TNXB encodes an extracellular matrix protein and is associated with connective tissue disorders." (PMID 38849516, 2024).
neurological disease (2 papers, 2012 to 2021). "Besides that, in this LD block, several variants act as eQTLs/sQTLs in the brain and whole blood, altering the expression of many genes already related to LOAD or other neurological diseases in human or animal studies, such as CELF1 itself, MADD, MYBPC3, NR1H3, NUP160, SPI1, and TOMM40." (PMID 34291080, 2021).
bacterial infections (1 paper, 2024). "Another target, Nr1h3 (or Lxrα), which plays a crucial role in the macrophage response to intracellular bacterial infections, inflammatory response, and metabolic homeostasis, showed the same pattern of expression, as observed in DMD samples." (PMID 38339055, 2024).
kidney disease (1 paper, 2023). "Healthy controls and kidney disease samples showed strong expression of DNL genes, including ACSS2, NR1H3 (liver X receptor α [LXRA]), NR1H4 (farnesoid X receptor [FXR]), SREBF1, SCAP, PLIN2, PLIN5, ACACAB, ATP citrate lyase (ACLY), and FASN in PT cells and some other tubule cells." (PMID 38051585, 2023).
NR1H3 also shares sentences with these, for which no sentence is quoted: Obesity (9 papers); glioblastoma (4); gallstones (3); type 2 diabetes mellitus (3); Alzheimer disease (2); cardiovascular disease (2); colorectal adenocarcinoma (2); diabetic kidney disease (2); lung fibrosis (2); prostate carcinoma (2); psoriasis (2); ANCA-associated vasculitis (1); arteriosclerosis (1); bacteremia (1); congenital heart defects (1); coronary artery disease (1); COVID-19 (1); dilated cardiomyopathy (1); dyslipidaemia (1); endometrial cancer (1); genetic disorder (1); giant cell arteritis (1); Glucose intolerance (1); Granuloma (1); hepatoblastoma (1); hyperlipidemia (1); hypertriglyceridemia (1); hypothyroidism (1); inflammation (1); Insulin resistance (1).
A further 10 diseases each share a sentence with NR1H3 in 1 paper.